HGF (hepatocyte growth factor)
Diseases named in the same sentence as HGF in open-access papers (continued):
Sharing a sentence is not in itself a finding about the gene and the disease.
cancer (1,459 papers, 1996 to 2026). A tumor composed of atypical neoplastic, often pleomorphic cells that invade other tissues. "The imbalance causes overactivation of HGF and leads to increased cancer cell proliferation, motility, and invasive activity through increased MET phosphorylation." (PMID 40299447, 2025). "STMN1S16 phosphorylation is associated with cancer cell proliferation, and HGF is a stromal cell growth factor that promotes DU-145 PCa cell proliferation." (PMID 40723207, 2025). "Currently, there is a widespread belief that HGF originates from intrahepatic normal or cancer-associated fibroblasts (CAFs)." (PMID 41048570, 2025). "Joffre reported that the presence of an activating mutation of MET in cancer cells would enhance oncogenic signal activity in the presence of HGF." (PMID 40299443, 2025). "For instance, hepatocyte growth factor (HGF) secreted by cancer-associated fibroblasts (CAFs) can enhance Wnt/β-catenin signaling in neighboring cancer cells, thereby promoting stemness, clonogenicity, and metastatic potential." (PMID 41373619, 2025). "In cancer, HGF is reported to be secreted mainly from cancer-associated fibroblasts (CAFs) in the paracrine fashion, though some cancers have the potential to express HGF in the autocrine style." (PMID 40299443, 2025). "Further, in vivo studies showed that TGFβRII‐deficient fibroblasts increase HGF expression, affecting neighboring epithelial cells and leading to the development of certain carcinomas." (PMID 39083441, 2025). "The MET proto-oncogene encodes the tyrosine kinase receptor for hepatocyte growth factor, which is often overexpressed in many human cancers." (PMID 39221422, 2024). "In cancer patients, low circulating HGF, low IL-6, and high CCR were associated with improved PFS and OS." (PMID 38776028, 2024). "Overexpression of c-MET and HGF is associated with poor prognosis or metastatic progression in several major cancers." (PMID 39335535, 2024). "The Met receptor and its associated ligand, known as HGF, play a pivotal role in the signaling pathways implicated in the development of cancer." (PMID 39130630, 2024). "Tepotinib inhibits cancer cell growth and induces regression of susceptible HGF-dependent and -independent tumors." (PMID 38339049, 2024). "HGF/c-Met signaling promotes a glycolytic phenotype in cancer cells, causing them to secrete more lactic acid, and the increased lactic acid inhibits CTL proliferation and activity." (PMID 39201787, 2024). "Dysregulated HGF/c-Met pathway has been implicated in multiple human cancers and has become an attractive target for cancer intervention." (PMID 38078363, 2024). "In cancers, the HGF pathway is associated with growth and metastasis, while in trophoblasts, it is associated with proliferation and survival." (PMID 36834865, 2023). "The HGF/MET pathway is known to be associated with the appearance of several attributes of cancer and is utilized as a relevant target across many solid tumors." (PMID 37170275, 2023). "In order to promote pro‐carcinogenic pathways, NF‐κB and STAT3 are activated, and mitogens such as amphiregulin, epiregulin, and hepatocyte growth factor (HGF) produced by TLR‐expressing fibroblast cells have cancer‐causing effects." (PMID 37706437, 2023). "Aberrant activation of the MET/HGF pathway has been found in many types of cancer and it is associated with disease progression, metastasis, and drug resistance." (PMID 37444518, 2023). "When HGF binds to c-MET in cancer cells, they are stimulated to produce uPA, causing more pro-HGF to become active HGF, which then binds to c-MET in PC cells." (PMID 37173787, 2023). "The cancer-associated fibroblasts (CAFs) have been found to secrete hepatocyte growth factor (HGF), thereby instigating resistance to pharmacological interventions targeting tyrosine kinases and the epidermal growth factor receptor (EGFR)." (PMID 37666809, 2023).
cancer (continued). "Particularly, the MET receptor tyrosine kinase (RTK) for hepatocyte growth factor (HGF) represents a model recapitulating both the classically associated functions of RTKs in cancer, as well as their involvement in rewiring the DDR machinery." (PMID 36494469, 2022). "We previously reported that modifications in cancer cell metabolism instruct cancer-associated fibroblasts to increase HGF production, sustaining an adaptive resistance response." (PMID 35351166, 2022). "Specifically, increased lactate secretion leads to upregulation of hepatocyte growth factor (HGF) production by cancer-associated fibroblasts in a nuclear factor KB-dependent manner." (PMID 36505831, 2022). "This study found that resistant tumors upregulated lactate production and nuclear factor kappa-B (NF-κB), which induced hepatocyte growth factor (HGF) transcription by adjacent cancer-associated fibroblasts." (PMID 35565690, 2022). "HGF released from CAFs activates Met in cancer cells, causing a resistance to epidermal growth factor receptor (EGFR) TKIs in lung and breast cancers." (PMID 33918653, 2021). "c-Met is a receptor tyrosine kinase that binds to hepatocyte growth factor and triggers various cancer-associated processes, including proliferation, angiogenesis, invasion, and epithelial–mesenchymal transition." (PMID 34680492, 2021). "It has been reported that autophagy, one of several cellular adaptive responses to therapeutic stresses caused by anti-cancer agents, is critical for the resistance to HGF/MET-targeted therapy." (PMID 34771620, 2021). "Different mechanisms of MET activation have been described in human cancer including protein overexpression, gene amplification, point mutation, exon 14 deletion and paracrine or autocrine activation via HGF." (PMID 34200749, 2021). "Aberrant expression of MET and its ligand hepatocyte growth factor is associated with drug resistance in cancer therapy." (PMID 34761497, 2021). "STMN1 regulated cancer-associated fibroblast (CAF) features through HSC by triggering the HGF/MET signaling pathway." (PMID 34178637, 2021). "Apart from effective exosome inhibitor, ferroptosis inducer Fe3+ was also unified into the HGF nanogroup, due to that this kind of oxidative cell death has been claimed to associate with T cell immunity and cancer immunotherapy." (PMID 34593794, 2021). "Tumors enriched in the carcinoma-associated fibroblasts involved in TME can secrete hepatocyte growth factor (HGF, ligand for c-Met receptor), and C-X-C motif chemokine 12 (CXCL12, THE ligand for chemokine receptor CXCR4)." (PMID 34944829, 2021). "The findings were correlated with a highly expressed cognate receptor of HGF/c-Met during inflammation and in cancer-associated lymphatic vessels in both in vitro and in vivo studies, suggesting a direct role of HGF with LECs." (PMID 33172072, 2020). "HGF secreted as inactive zymogen (pro-HGF) from cancer associated stromal fibroblasts, and the proteolytic activation by several TTSPs including matriptase and hepsin is required." (PMID 32290402, 2020). "Many human cancers involve abnormal expression of HGF/SF or c-Met or activation of c-Met kinase mutations." (PMID 32521825, 2020). "According to Demkova and Kucerova, one of the important signaling pathways that has been implicated in many cancers’ metastatic spread is signaling by HGF/MET." (PMID 33066121, 2020). "Several in vivo studies have demonstrated that the activation of the HGF/c-Met signaling pathway causes cancer invasion and metastasis, which supports and broadens the results of this study." (PMID 32630328, 2020). "HGF levels in serum have been reported to be of diagnostic or prognostic value in different cancers by several investigators." (PMID 33233528, 2020). "Dysregulation of MET in several cancers occurs due to its overexpression, overexpression of HGF, activating mutations, or an autocrine/paracrine/endocrine loop dysregulation." (PMID 32722184, 2020).
cancer (continued). "In this review, we discuss the regulatory association between ncRNAs and the HGF/c-Met axis by providing a comprehensive understanding of their potential mechanisms and roles in cancer development." (PMID 32083078, 2020). "Tian and co-workers have identified a mechanism by which MZF1 can affect gene expression via cancer-induced allelic mutations that result in a novel transcription factor co-operation at the promoter of the hepatocyte growth factor gene HGF." (PMID 31963147, 2020). "cMET is a receptor for hepatocyte growth factor (HGF), which shows increased levels and association with poor clinical outcome in human cancer." (PMID 32983165, 2020). "Cancer-associated fibroblasts also reprogram the ECM to retain more paracrine HGF, which in turn positively affects the activation of c-MET and its downstream signaling pathways, thereby causing further resistance to MET inhibitors." (PMID 33271944, 2020). "In turn lactate instruct cancer-associated fibroblasts (CAFs) to produce hepatocyte growth factor (HGF), which activates MET and sustains the development of adaptive resistance to TKIs." (PMID 33302515, 2020). "Later studies in colorectal cancer showed that cancer-associated fibroblasts secrete hepatocyte growth factor, osteopontin, and stromal-derived factor 1α, which activate the WNT pathway to promote cancer cell stemness." (PMID 31355143, 2019). "One of the important signaling pathways which was implicated to play role in many cancers including metastatic spread is signaling by hepatocyte growth factor (HGF) via its cognate receptor c-Met with tyrosine kinase activity." (PMID 29455657, 2018). "Both HGF and/or NRG1β are highly expressed by cancer associated fibroblasts in the breast and high expression has been associated with poor prognosis and drug resistance." (PMID 29550255, 2018). "Activation of the HGF/c-Met signaling pathway is a hallmark of cancer cells and both HGF and c-Met have emerged as therapeutic targets." (PMID 30214428, 2018). "Rather, cancer-associated fibroblasts are primarily responsible for HGF production, and as a result activate c-Met paracrinally." (PMID 30214428, 2018). "Because pro-HGF is frequently expressed in various human cancers and abundantly expressed by cancer associated stromal cells, pro-HGF activation systems are also major targets in anti-MET treatment." (PMID 29890660, 2018). "In fact, HGF appears to be a crucial protein for the cross-talk between cancer cells and cancer-associated fibroblasts." (PMID 28420162, 2017). "In this study we demonstrated that HGF, commonly produced by cancer-associated fibroblasts, confers resistance to MET kinase inhibitors in MET-amplified NSCLC cells." (PMID 28968967, 2017). "Aberrant cMET/HGF expression is observed in numerous types of cancer and is associated with a poor prognosis." (PMID 29228696, 2017). "More commonly HGF is produced by stromal cells, such as cancer-associated fibroblasts, and triggers MET activation in a paracrine fashion." (PMID 28420162, 2017). "Upregulation of HGF has been frequently observed in various cancers wherein higher expression of HGF is associated with poorer prognosis in cancer patients." (PMID 29133945, 2017). "A hallmark of cancer progression, angiogenesis is stimulated by HGF-induced production of well-established pro-angiogenic factors including interleukin (IL)-8, vascular endothelial growth factor (VEGF), and platelet-derived growth factor (PDGF)." (PMID 28441771, 2017). "Specifically, one recent study demonstrated that HGF can be secreted from cancer-associated fibroblasts for the initiation of HCC in the context of cirrhosis." (PMID 28587113, 2017). "Hepatocyte growth factor (HGF) is a major component of the fibroblast secretome and cancer-associated fibroblasts have been shown to promote epithelial-mesenchymal transition, cell scattering and migration of cancer cells in an HGF-dependent manner." (PMID 28420162, 2017).
cancer (continued). "Rather HNSCC cancer-associated fibroblasts (CAF) have been shown to secrete HGF, suggesting an HGF-c-Met paracrine driven tumorigenesis." (PMID 29231907, 2017). "Constitutive HGF/MET signaling is a hallmark of cancer cells and HGF and MET have both emerged as valid therapeutic targets." (PMID 28420162, 2017). "Members of the HGF/c-Met/ETS-1 signaling pathway are expressed in human cancers, and a high level of ETS-1 protein is associated with poor prognosis, disease progression, and metastasis." (PMID 29312607, 2017). "The significant associations were found between HGF expression in cancer cells and pathologic differentiation (p=0.001)." (PMID 27374174, 2016). "Mutations of Met are, however, rare events in cancer and aberrant activation mostly arises from over-expression of the receptor in cancer cells and/or increased secretion of HGF from stromal mesenchymal cells." (PMID 27270323, 2016). "Activated HGF/c-Met signaling is known to promote cell scattering which stimulates cells to abandon their original environment, a hallmark of cancer invasiveness and metastasis." (PMID 27086914, 2016). "We found that cloudberry extract potently inhibited HGF-induced and Met receptor-mediated cancer cell migration and underlying downstream signaling to ERK and AKT in vitro." (PMID 27270323, 2016). "For example, MET gene mutation and amplification represent one of the major mechanisms causing constitutive active HGF/c-MET signaling in cancer cells." (PMID 27923392, 2016). "Through studies examining metabolic contributions to growth factor signaling (data not published), we discovered that monocarboxylate transporters (MCTs) are important factors associated with EGF- and HGF-induced cancer cell motility." (PMID 27127175, 2016). "Cancer-associated fibroblasts promote malignant cell growth and survival at least in part by HGF secretion." (PMID 27121052, 2016). "NRP-1 is also implicated in the activation of HGF-induced signaling and cellular responses in cancer cells." (PMID 26795388, 2016). "Previous studies have indicated that cancer associated fibroblasts (CAF) stimulates cancer cell motility or invasion by producing soluble factors such as Hepatocyte growth factor (HGF), Transforming growth factor (TGF)-β, CXCL12." (PMID 27136922, 2016). "The MNNG-HOS transforming gene (MET) encoding the receptor tyrosine kinase for hepatocyte growth factor (HGF) is involved in cancer progression and metastasis formation, and suggests poor prognosis in early stage and second-line HCC patients." (PMID 27579536, 2016). "Overexpression of HGF and c-Met has been detected in numerous cancer types and is associated with a worse prognosis." (PMID 26090722, 2015). "HGF immunoreactivity was mainly present in the cytoplasm of carcinoma cells and intratumoral stromal cells, including cancer-associated fibroblasts (CAF)." (PMID 26036285, 2015). "Many studies reveal that HGF/c-MET axis is implicated in various human cancers, and genetic and epigenetic gain of functions of this signaling contributes to cancer development through a variety of mechanisms." (PMID 28536400, 2015). "The dysregulation of this pathway has been implicated in cancer initiation, development and even metastasis, which suggested that targeting to HGF/MET axis is a potential strategy in cancer targeted therapy." (PMID 26254225, 2015). "It has been previously reported that HGF has the most potent effect on the promotion of cancer cell infiltration, the cell migration associated with the degradation of extracellular matrix components, including the basement membrane and collagen." (PMID 25592281, 2015). "Activation of the HGF/c-Met pathway leads to simultaneous activation of multiple signal transduction pathways that promote the infiltration of cancer cells and is considered to underlie the potent infiltrative/stimulatory effect of HGF." (PMID 25592281, 2015).
cancer (continued). "The Hepatocyte growth factor (HGF)—mesenchymal-epithelial transition (MET) pathway is deregulated in several cancers and is associated with aggressive phenotype and worse prognosis." (PMID 28548075, 2014). "In conclusion, with respect to patients undergoing cancer therapy with HGF/Met inhibitors alone or in combination, the risk of cardiotoxicity is prominent and the evaluation of cardiac stressors in the design of the therapeutical approach is advisable." (PMID 28548070, 2014). "HGF is a pleiotropic factor involved in the enhancement of metastatic potential of cancer cells and MET encodes for its cellular receptor c-Met." (PMID 24952592, 2014). "A dysfunctional HGF/c-Met axis has been implicated in the development, invasion and angiogenesis of cancers, and an increasing number of studies have revealed the specific mechanism." (PMID 25202379, 2014). "MET and its ligand, hepatocyte growth factor (HGF), have been implicated in the progression of many cancers." (PMID 24205338, 2013). "MET is a receptor tyrosine kinase that is activated by the ligand HGF and has been shown to be constitutively expressed, mutated, or over-expressed in many different cancer cell types." (PMID 24326130, 2013). "The newly discovered metastasis-associated in colon cancer-1 (MACC1) gene is a key regulator of the HGF/MET pathway." (PMID 22251819, 2012). "Our findings of the potential association between CYP19A1 including the rs749292 variant and HGF levels suggest that CYP19A1 is also likely associated with cancer progression due to elevated HGF levels." (PMID 22848710, 2012). "A limitation of this study is that, because of the relatively small number of cancer deaths, we were unable to investigate the association between HGF and particular malignancies." (PMID 22672958, 2012). "HGF is strongly associated with the progression of cancer cells to invasive phenotypes and the development of distant metastases." (PMID 22018031, 2011). "While transgenic HGF mice were predisposed to a low incidence of many types of cancers, including skeletal muscle-derived tumors, transgenic HGF mice with a targeted deletion of the INK4A/ARF locus had a near complete penetrance of eRMS in young animals." (PMID 21253475, 2011). "HGF accomplishes most of the functions of the invasive program in carcinomas (loss of adhesive junctions, motility, angiogenesis, and survival/apoptosis)." (PMID 20667141, 2010). "But despite all these optimistic biologic and clinical aspects, it must be borne in mind that HGF is one of the numerous protein factors associated with cancer and cancer progression." (PMID 17576468, 2007). "The c-MET/HGF pathway has gained considerable interest through its apparent deregulation by overexpression or gain-of-function mutations in c-MET in various cancers, including lung cancer." (PMID 17667909, 2007). "Moreover, our study demonstrated that KDM5B is associated with WNT/β-catenin signaling in the cytoplasm, HGF signaling in cancer, sphingolipid metabolism, and the Hippo pathway." (PMID 39239542, 2024). "However, it is worth noting that only patients with tumors overexpressing c-Met can benefit from HGF/c-Met targeting therapy, as these interventions inhibit typical c-Met-associated processes such as oncogenesis, cancer metastasis, and drug resistance." (PMID 38137344, 2023). "Therefore, the HGF/c-MET signaling pathway has emerged as a crucial field for investigating the mechanisms underlying cancer development and identifying potential therapeutic targets." (PMID 37919751, 2023). "In addition, HGF alteration was also detected only in BM and CSF ctDNA, which is associated with poor prognosis in cancer patients." (PMID 36495130, 2023). "It would be intriguing to look into whether HGF levels in the cancer group were associated with DIC scores, at least in those patients who had high levels of inflammatory cytokines." (PMID 37504277, 2023). "Hyperactivity of HGF/c-MET signalling is considered a hallmark of cancer." (PMID 36591282, 2022).